PHF19 (PHD finger protein 19)
Diseases named in the same sentence as PHF19 in open-access papers (continued):
Sharing a sentence is not in itself a finding about the gene and the disease.
tumor (23 papers, 2012 to 2025). "If confirmed, this link would imply clinical relevance for the PHF19-207 transcript as a marker related to inflammation-associated premalignant lesions and as a potential target for modulating inflammation to reduce tumor progression." (PMID 40563408, 2025). "The expression of PHF19 has here been linked to the expression of the tumor-suppressive miRNA hsa-miR-195-5p." (PMID 37107696, 2023). "Although the PHF19 gene is known to encode a protein with tumor-promoting properties, the specific role of its non-coding transcript PHF19-207 is unknown." (PMID 40563408, 2025). "This could prove a useful finding since currently the association between PHF19 and tumor aggressiveness is at the patient level whereas our results imply that only a fraction of malignant plasma cells in a MM tumor actually overexpress PHF19." (PMID 35105355, 2022). "As expected, the expression of the PHF19-207 transcript in biopsied mucosa samples was lower compared to that in tumor tissue samples, which was aligned with the results from Xena Browser platform." (PMID 40563408, 2025). "The results of the transcriptional profiling confirm biomarker potential and are also in line with the proposed tumor-promoting role of the PHF19-207 transcript." (PMID 40723829, 2025). "This concept requires further investigation, particularly to clarify the extent to which the PHF19-207 transcript expression is influenced by local inflammation or other non-tumor cells present in the colon tissue." (PMID 40563408, 2025). "When comparing samples of tumor tissue to samples of healthy intestinal mucosa, the differential expression of the PHF19-207 transcript was even more pronounced (p < 0.001)." (PMID 40563408, 2025). "Through the modulation of EMT marker expression, PHF19 boosts the migratory and invasive abilities of tumor cells, thereby promoting CRC malignancy." (PMID 38813086, 2024). "Then we used Zhongshan cohort to verify the relationship between PHF19 protein expression and clinicopathological data, we found that high PHF19 protein expression indicated worse tumor stage and more likely tumor metastasis, especially liver metastases." (PMID 34141488, 2021). "As a transcription factor that regulates chromatin function, PHF19 has also been proven to regulate tumor EMT progression in a variety of tumor studies." (PMID 34141488, 2021). "In a mouse model of antitumor function, Phf19 overexpressing T-cells displayed limited senescence and sustained cytokine production and anti-tumor activity resulting in increased mice survival compared to controls." (PMID 34857028, 2021). "Western blot showed that the key proteins of EMT, β-catenin, Twist, and N-cadherin, were up-regulated, and E-cadherin was down-regulated, indicating that PHF19 promotes tumor cell invasion and metastasis by regulating EMT-related molecules." (PMID 34141488, 2021). "Yet, more exact mechanisms underpinning the effects of PHF19 on tumor immunity remain to be elucidated." (PMID 35069553, 2021). "Combining PHF19 with other independent prognostic factors such as age and tumor TNM staging can build a good prognostic judgment model for CRC patients." (PMID 34141488, 2021). "In the meanwhile, the role of PHF19 in tumors has been confirmed to be closely related to the process of tumor cell proliferation and metastasis." (PMID 34141488, 2021). "Through subcutaneous tumor formation experiments in nude mice, we found that compared with the control group, mice in the PHF19 overexpression group obtained larger tumor tissues and heavier tumors after 28 days." (PMID 34141488, 2021). "To determine the expression profiles of PHF19 in human normal tissues, we investigated the mRNA expression patterns of PHF19 in various non-tumor tissues and single cell types based on publicly available genome-wide expression data." (PMID 35069553, 2021).
tumor (continued). "Immunohistochemical staining showed that PHF19 expression was substantially reduced in the PHF19-knockdown tumor samples." (PMID 30323224, 2018). "When PHF19 expression was restored in PHF19-knockdown LN-229 cells, the tumor formation and colony formation capacities were also restored." (PMID 30323224, 2018). "This raised the possibility that the selection for Sdc2 and Phf19 expression during mammary tumorigenesis is a collaborative event with other MMTV activated genes in the same tumor." (PMID 23131872, 2012). "The PHF19-207 transcript may be involved in tumor initiation or maintenance by influencing the key signaling pathways associated with cell proliferation, apoptosis resistance, or immune evasion." (PMID 40563408, 2025). "According to previous data, the increased expression of the PHF19-207 transcript in tumors can be attributed to tumor cells, but the exact cellular origin of the observed differences remains unclear." (PMID 40563408, 2025). "Since the PHF19-207 transcript is present at low levels in healthy cells but is significantly elevated in tumor tissues, its presence in cell-free RNA may serve as an indicator of malignancy." (PMID 40563408, 2025). "Bioinformatics revealed that PHF19 might affect tumor malignant phenotype by regulating the cell cycle in CRC." (PMID 34141488, 2021). "Tumor formation experiments in nude mice showed that overexpression of PHF19 could promote tumor proliferation in vivo." (PMID 34141488, 2021). "Besides, we found that the oncogene effect of PHF19 in CRC is very likely to be achieved by affecting tumor progression and regulating the cell cycle." (PMID 34141488, 2021). "Finally, tumor formation experiments in nude mice were used to verify the role of PHF19 of tumor proliferation in vivo." (PMID 34141488, 2021). "Hypermethylated promoter regions in ALK tumor cells showed strong enrichment of binding sites for proteins associated with chromatin remodeling in ESC, in particular PRC associated proteins including CBX7, EZH2, MTF2, PHF19, RING1B, RNF2, and SUZ12." (PMID 33310759, 2021). "The epigenetic related regulator PHF19 participates in the carcinogenic progression of multiple cancers, and may contribute to the immune infiltration in tumor microenvironment." (PMID 35069553, 2021). "Although investigators have gained some understanding of the regulation of Polycomb activity by PHF19, little is known about whether and how it drives tumor initiation, progression, and metastasis." (PMID 35069553, 2021). "The results determined a positive relationship between PHF19 level and advanced tumor stages." (PMID 35069553, 2021). "According to our results, we supposed that PHF19 may affect tumor progression by affecting the metastasis ability of CRC." (PMID 34141488, 2021). "Nevertheless, more drug should be detected to determine whether the function of PHF19 in CFG’s anti-tumor effect is specific." (PMID 32180719, 2020). "Harnessing miR-155 and Phf19 might represent an effective strategy to enhance PRC2 function in tumor-reactive T cells to sustain engraftment, cytokine production, and ultimately antitumor immunity." (PMID 31089138, 2019). "To explore the roles of PHF19 in colony formation and tumor formation of GBM cells, we employed soft agar assays and orthotopic implantation, and the results showed that the colonies were smaller and fewer in the PHF19-knockdown U-87 MG and LN-229 cells than in the control cells." (PMID 30323224, 2018). "Correspondingly, PHF19 and Ki-67 levels were rescued in the tumor samples." (PMID 30323224, 2018). "Moreover, the PHF19-207 transcript might also be suggested to participate in modulating the inflammatory response in the tumor microenvironment." (PMID 40563408, 2025). "In addition, miR-211 could sponge lncRNA MALAT1 to suppress tumor growth and progression through inhibiting PHF19 in OC." (PMID 33413565, 2021).
tumor (continued). "Lastly, to evaluate whether the epigenetic reprogramming mediated by Phf19 result in augmented antitumor function we adoptively transferred pmel-1 cells overexpressing Phf19, Phf19mut, or Thy1.1 into tumor-bearing mice in conjunction with administration of gp100-VV and IL-2." (PMID 31089138, 2019). "According to prior surveys, MPs can downregulate specific genes in tumor cells, such as BCAS3, PHF19, and PRKCD, whose expression has been suppressed by microplastics in previous studies." (PMID 41378310, 2025). "Among them, PHF19, AURKA, CHAF1B and AURKB were up-regulated in the tumor group, NAP1L2, TONSL, SATB2 and HDAC9 were down-regulated in the tumor group." (PMID 38212708, 2024). "The analysis of showed that PHF19, AURKA, CHAF1B and AURKB were up-regulated in the tumor group, NAP1L2, TONSL, SATB2 and HDAC9 were down-regulated in the tumor group." (PMID 38212708, 2024). "Conversely, some well-known factors related to tumor growth promotion, such as HMGA1, GTF3A, PHF19, CENPX, and MBD2, were upregulated." (PMID 35935940, 2022). "PHF19 activated PRC2 and promoted the spread of H3K27me3, thereby enhancing its promotion of tumor formation." (PMID 34141488, 2021). "The results of correlation analysis based on clinicopathological data indicate that PHF19 mRNA was closely related to the depth of tumor invasion, and the relatively higher expression of PHF19 mRNA in the later T stage suggested that it might be related to tumor progression." (PMID 34141488, 2021). "Tumor formation was significantly slower and tumors were smaller in NOD/SCID mice injected with PHF19-knockdown LN-229 cells compared with control mice." (PMID 30323224, 2018). "For some of the microRNA molecules predicted to bind to PHF19-207, anti-tumor roles were demonstrated, while others are not yet characterized." (PMID 40723829, 2025). "This may explain why we quantified the lowly expressed PHF19-207 transcript in the HCEC-1CT cell line and observed upregulation in cell lines representing other stages of tumor development." (PMID 40723829, 2025). "Analysis of publicly available sequencing data showed a slight increase in the expression of PHF19-207 in the tumor in comparison to normal tissue, but without statistical significance." (PMID 40723829, 2025). "In this study, we found slightly increased the PHF19-207 transcript expression levels in inflamed vs. non-inflamed gut mucosa, suggesting the involvement of the stromal component of the tumor in the obtained expression profiles." (PMID 40563408, 2025). "PHF19, a member of the poly-comb group of proteins, which maintains the repressive transcriptional status of genes involved in development, was previously shown to be upregulated in human HCC and to promote tumor cell proliferation." (PMID 35563834, 2022). "FKBP11, PHF19, ARPC3, and MS4A14 were overexpressed in tumor tissues." (PMID 35651604, 2022). "In conclusion, our study revealed for the first time that the expression of the PHF19 gene was up-regulated in CRC tissues and was closely related to tumor progression and the prognosis of patients with CRC and could be an independent prognostic factor." (PMID 34141488, 2021). "Similarly, the tumor-enriched PHF19 intronic APA transcript generated a truncated PHF19 protein lacking one PHD finger domain and the Mtf2_C (polycomb-like MTF2 factor 2) domain." (PMID 39349823, 2024). "Surprisingly, not like the compound, none of these ingredients could reduce the expression of PHF19 alone, suggesting that the interaction among these ingredients and the integrity of this compound are vital for the anti-tumor function of CFG." (PMID 32180719, 2020). "Our research proved that PHF19 could be an independent prognostic factor for CRC, PHF19 promoted the proliferative ability and the invasion and metastasis of CRC by up-regulating the expression of key molecules related to cell cycle and EMT pathway in vitro, promoting tumor proliferation in vivo." (PMID 34141488, 2021).
colon (1 paper, 2025). "This study suggests that the PHF19-207 transcript may serve as a marker of colon malignancy, regardless of whether it has a direct functional role." (PMID 40563408, 2025).
infection (1 paper, 2020). The state of being infected such as from the introduction of a foreign agent such as serum, vaccine, antigenic substance or organism. "After infection with the PHF19 overexpression or shRNA lentivirus for 72 h, we ensured the overexpression and silencing efficiencies using Western blot analysis and all the lentivirus were well functioned." (PMID 32180719, 2020).
PHF19 also shares sentences with these, for which no sentence is quoted: multiple myeloma (7 papers); pancreatic cancer (3); acute myeloid leukemia (1); acute promyelocytic leukemia (1); asthma (1); childhood asthma (1); diffuse large B-cell lymphoma (1); head and neck cancer (1); hematologic malignancies (1); influenza (1); lung carcinoma (1); lymphoma (1); neuroblastoma (1); non-small cell lung carcinoma (1); osteosarcoma (1); rectal cancer (1); sarcoma (1); skin cutaneous melanoma (1); thymoma (1); viral infection (1).